CD4 (CD4 molecule)
Diseases named in the same sentence as CD4 in open-access papers (continued):
Sharing a sentence is not in itself a finding about the gene and the disease.
infection (continued). "Collectively, these Envs were significantly less able to mediate CD4-independent infection compared to the control SHIV Envs, which varied from low to high CD4 independence (p < 0.0001)." (PMID 30415390, 2019). "Here, we locally administered low and high inoculum of lymphocytic choriomeningitis virus (LCMV) in mice to follow activation parameters of Ag-specific CD4+ and CD8+ T cells in draining lymph nodes (LNs) during the first 72 h post infection." (PMID 31552034, 2019). "These epitopes can be presented to CD4+ or CD8+ T cells via major histocompatibility complex class-I (MHC-I) and class-II (MHC-II) and start to clear the infection." (PMID 31725727, 2019). "Among them, Pre-PrEP area infection that is a proxy of delay in HIV testing concerned 77% of our population, of whom 35% were born in west or central Africa, 31% with CD4 cell count less than 200/mm3 and 20% between 200 and 350/mm3." (PMID 30909885, 2019). "Additional studies will also better characterize HCV-specific CD4 T-cells and help understand different transcriptional states of HCV-specific CD8 T-cells at the site of infection, the liver." (PMID 31357397, 2019). "PMHCII-NP treated NOD.c3c4 mice mounted protective immunity against the PR8 infection, as documented by decreased viral load in lung tissue and clinical signs of active infection, despite systemic presence of cognate TR1-like CD4+ T-cells." (PMID 31089130, 2019). "Ratifying this phenomenon, CD4+ and CD8+ T cells have been found against Brucella in mouse, cattle, and human infections." (PMID 31572389, 2019). "At day 10 post infection, T-bet expression in TFH and TH1 cells had decreased back to levels ~6- and 13-fold higher than those in naïve CD4+ T cells." (PMID 30984183, 2019). "We also extended the analysis of HCV-specific CD4+ T cells and compared the TIGIT and CD226 expression of HCV-specific CD4+ versus CD8+ T cells of acutely and chronically versus HCV patients with spontaneous resolution of infection." (PMID 31337800, 2019). "We have noted that DNA immunization of mice enhanced the frequency of Th1 effector CD4+T cells and poly-functional, cytotoxic CD8+T cells that had the capability to respond to challenge infection with further expansion." (PMID 31293599, 2019). "IAV-specific regulatory T cells (Treg, Foxp3+) have been shown to be important in dampening inflammatory signals and proliferation of IAV-specific CD4 and CD8 T cells during infection, thereby preventing excessive damage to host tissues." (PMID 31632414, 2019). "The difference of p24 production from HIV-1NL4-3VifY40H infection between shRNA-NC and shRNA-KD-USP49 in primary CD4+ T cells at several time points was statistically analyzed." (PMID 31397674, 2019). "No remarkable differences were observed in the percentage of CD3+, CD4+, and CD8+ cells, as well as the ratio of CD4+/CD8+ among the three treatments 3 and 7 days post-infection (P > 0.05)." (PMID 29948799, 2019). "For peripheral blood CD4+ and CD8+ T cell percentages, a significant difference (p ≤ 0.05) was detected post infection." (PMID 31114576, 2019). "Our observations also suggested that if animals were unable to mount an effective CD4 response, animals not only required Gag or Pol-specific systemic CD8 T cell immunity, but also humoral immunity for effective control of infection." (PMID 30952887, 2019). "It is worth noting that despite being dispensable, CD4+ and CD8+ T cells proliferate and become activated following infection of mice with ZIKV, and both T and B cells are critical to protect ZIKV-immune mice from intracranial challenge with the virus." (PMID 31511023, 2019). "To assess the requirement for CD4+ T cells for viral clearance after IVag infection, we quantified infectious ZIKV particles in serum, vaginal washes, and the FRT on day 10 post-IVag infection of control or anti-CD4 Ab-treated LysMCre+Ifnar1fl/fl mice." (PMID 30677097, 2019).
infection (continued). "Cellular responses seem to be initially related to protection against disease progression and later clearance of infection in which both CD8+ and CD4+ T cells play a crucial role by producing IFN-γ." (PMID 31075819, 2019). "Neutrophil dysfunction is more evident in the later stages of infection in patients with high HIV-1 plasma concentrations and lower CD4 lymphocyte counts." (PMID 30972057, 2019). "Substantial effort using patient samples and mouse models has resulted in the identification of many CD4+ and CD8+ T cell immunodominant epitopes during DENV and ZIKV primary and secondary infections." (PMID 31244855, 2019). "Over the course of infection, plasma SHIV RNA was inversely correlated with peripheral (r = −0.44; P value of 0.03) and colonic (r = −0.62; P value of 0.005) CD4+ T cells." (PMID 29563297, 2018). "The absolute numbers of peripheral white blood cells, as well as CD4, CD8, and CD21 cells progressively declined over 8.20 years of FIV infection." (PMID 29794987, 2018). "Eventually, the T cells at the site of initial infection upregulate CD103 and CD69 suggesting they assume the CD4+ TRM phenotype between 30 and 90 days post infection." (PMID 30038624, 2018). "Most changes in increasing trend of CD3+, CD4+, and CD8+ numbers were occurred in two first weeks after the infection." (PMID 30147640, 2018). "Mice depleted of CD4+ and CD8+ T cells during F. holartica LVS infection are chronically infected suggesting this MAIT population controls bacterial burdens, but does not mediate clearance." (PMID 29682484, 2018). "Comparable CD4+ and CD8+ T-cell proliferative responses were triggered by TB40E-infected or ΔUS2–11-infected Mφ at all tested time points after infection." (PMID 29887865, 2018). "We also evaluated lymphoid cell subsets by characterizing CD4+, CD8+, and γδ-TCR+ T cells in the lungs after infection." (PMID 29698474, 2018). "In order to increase the frequency of liver Trm, we infected mice i.v. with Lm and analyzed liver CD4+ and CD8+ Trm 7 weeks after infection." (PMID 30038627, 2018). "Consistent with other studies, during acute infection stage, the percentages of CD38 and HLA-DR coexpression on CD4+ T cells was negatively correlated with CD4+ T cell count (r = −0.34, p = 0.08) and positively correlated with pVL (r = 0.88, p = 0.03)." (PMID 29636753, 2018). "About 30% of CD4 T cells were DNGR-1+ in naïve mice of both groups; this percentage decreased during the first 3 weeks of infection to increase again at d28 p.i., suggesting that the majority of CD4+ DCs derived from monocytes during acute VL." (PMID 29472618, 2018). "Antigen-specific CD4 and CD8 T cells are known to be primed during either oral or i.v. infection, and memory T cells form that protect against secondary challenge using either infection model." (PMID 29361677, 2018). "We then co-cultured the activated CD4+ T cells alone (ACT), with LEC+, or with LEC- and observed the corresponding infection rates 3 days post infection." (PMID 30285810, 2018). "Because T cells were shown to be important in the control of experimental PCM, we decided to investigate CD4+ and CD8+ T cells in the lung of TLR3−/− and WT mice after 30 days of infection." (PMID 30687643, 2018). "An increased presence of IFN-γ+ and IL-17+ CD4+ T cells was seen at weeks 6 and 10 after infection, while only at the first period studied IL4+ CD4+ T cells appeared in decreased numbers." (PMID 30410119, 2018). "All monkeys experienced moderate increases in numbers of peripheral CD3+CD4+ T cell and CD3+CD8+ T cell during the early infection course followed by a transient decrease." (PMID 29967568, 2018). "There was a slight increase in the CD4+ and CD8+ T cell population early (3 days post-infection) after infection but essentially normal amounts up to 28 days post-infection in BALB/c mice." (PMID 30500862, 2018).
infection (continued). "Once CD4+ T cells arrive, they release interferon gamma (IFN-γ) and other cytokines required for CD8+ T cell recruitment to the infection site." (PMID 29698393, 2018). "The analysis of the functional profile of CD4 T cells revealed that ILC1s are dispensable for the induction of IFN-γ and TNF-α in this experimental in vitro infection model." (PMID 29623077, 2018). "Comparable numbers of LCMV-gp-specific CD4 T cells also were detected in both genotypes eight days after infection, suggesting that CD2AP is dispensable for priming and initial expansion of LCMV-specific CD4 T cells." (PMID 29734372, 2018). "We have used CD3+, CD4+, and CD8+ homolog antibodies to describe lymphocyte distribution changes in the infection period according to the vaccine type and Newcastle challenge." (PMID 30147640, 2018). "To confirm Treg depletion in these mice, we measured the frequency of Foxp3+cells among CD4+ T cells in MOIL and CLN, on day 1 after re-infection." (PMID 30197637, 2018). "During experimental infection, antigen-specific and IFN-γ expressing CD4+ and CD8+ T cells are recruited to the lung tissue and airway which peak 8–10 days post-infection." (PMID 30513770, 2018). "First, we investigated the frequency of CD4+CD25+Foxp3+ Treg in B. bronchiseptica infected mice, in comparison to control mice on days 7, 21, and 47, post infection." (PMID 30200513, 2018). "Next, we carried out a detailed characterization of the development of CD4+ and CD8+ T cell responses to several immunodominant EBV lytic and latent antigens in IM patients from primary infection to long term persistence by multi-color flow cytometric assays." (PMID 29599759, 2018). "Prior to YFV-17D infection and 5 days post infection, NFA2-HIS/Flt3LG mice were treated with anti-CD4 (α-CD4) or anti-CD8 (α-CD8) antibodies (n = 4 per group), which have previously been used to deplete CD4+ and CD8+ T cells, respectively, in humanized mice." (PMID 30487575, 2018). "In vitro, it is difficult to infect resting CD4+ T cells with HIV-1, but infections readily occur in vivo." (PMID 30285810, 2018). "In this study, 14 patients with CAEBV (aged 18-64 years; five males, nine females; CD4 type: n = 4; CD8 type: n = 4; CD56 type: n = 3; CD4 and CD56 double infection: n = 2; and CD4 and CD8 double infection: n = 1) were investigated." (PMID 30123428, 2018). "The T-lymphocyte cellular responses are crucial in controlling infection, as evidenced by the increased disease severity in HIV-infected patients with CD4 counts less than 100 cells/microL." (PMID 29672572, 2018). "Expression of CD25 and CD69 peaked at day 5 post-infection and was significantly higher in MAIT cells than conventional CD4+ or CD8+ T cells, persisting until day 13 post-infection." (PMID 30413689, 2018). "An often-overlooked effector function of memory CD4 and CD8 T cells is the promotion of an inflammatory milieu at the initial site of infection that mirrors the primary encounter." (PMID 29992170, 2018). "In infections with MVA-HCV and MVA-HCV ΔC6L, there was a lower recruitment in the total number of specific immune cell types (DCs, NKs, NKT cells, and CD4+ and CD8+ T cells) than for MVA-WT at 24 h post inoculation." (PMID 30096846, 2018). "This is reflected in the rise in median CD4 count representing a healthier population of PLHIV, contributing to the observed decline in infections." (PMID 29879977, 2018). "As expected, CD4-depleted BALB/c mice treated with PBS, PBS-liposomes, or clodronate-liposomes developed high fungal lung burdens after infection as determined by qPCR and GMS staining of cysts." (PMID 30283457, 2018). "Our TZM-bl results further support a role for GR in mediating MPA-induced infection via changes in CD4 and CCR5 levels, since RU486 significantly inhibited the MPA-induced increase in CCR5 and CD4 mRNA levels." (PMID 29698514, 2018). "The C-type lectin also facilitates trans infection of HIV-1 from DC, as well as B cells, to CD4+ T cells." (PMID 29643243, 2018).
infection (continued). "Briefly, CD4+ T-cells were purified from blood of four healthy donors and activated for 72 hr with αCD3/CD28 beads and 20 U/ml IL-2 before infection with HIVGKO." (PMID 29714165, 2018). "This concept stems from observations made over 15 years ago that, soon after infection, high levels of viral replication occur in GALT and a large fraction of gut CD4+ T cells are consequently lost." (PMID 29478152, 2018). "TLR4, which was up-regulated 2.6-fold in CD4+CD25+ T cells from B. bronchiseptica carriers, compared to uninfected controls, has been described to play a role in very early infection with B. bronchiseptica and to affect transmission." (PMID 30200513, 2018). "Peripheral CD4+ and CD8+ T cells were efficiently depleted in α-CD4 and α-CD8-treated NFA2-HIS/Flt3LG mice, respectively, prior to infection." (PMID 30487575, 2018). "At an early stage of the infection (4 DPI), ILC3 are the major source of IL-22 whereas CD4+ T cells secrete IL-22 at a later stage (after 9 DPI)." (PMID 30365535, 2018). "The number and activation of F4/80+ macrophages, CD11b+CD11c+ dendritic cells (DCs) as well as CD4+CD25+ and CD8+CD69+ T lymphocytes were determined by flow cytometry in DT-treated and control DEREG mice at weeks 6 and 10 of infection." (PMID 30410119, 2018). "After infection, DCs from MLN of developmentally exposed adult offspring were co-cultured with naïve CFSE-labeled naïve CD4+ T cells from OTII TCR transgenic mice." (PMID 30412605, 2018). "At 72 h post-treatment, CD4+ T-cells were infected with an X4-tropic GFP-expressing viral strain, and infection was monitored during 7 days by flow cytometry to evaluate % of infected cells (GFP+) and by ELISA (p24 antigen) to evaluate viral production." (PMID 29997630, 2018). "These Env/CD4-mediated events increase the probability of HIV-1 Env-CD4/coreceptor interactions, potentiating fusion pore formation, and thus HIV-1 entry and infection." (PMID 29636433, 2018). "During cis-infection, DCs and macrophages are productively infected and transmit HIV-1 to CD4+ T cells through a VS-like structure." (PMID 30055632, 2018). "On day 3 post-infection, adoptively transferred CD44+CD4+T-bet+CD62L− cells were detected in the ear while CD44+CD4+T-bet+CD62L+ cells populated draining lymph nodes (dLNs) but not skin." (PMID 29922288, 2018). "CD4+ T cells were stimulated with anti-CD3/CD28 antibodies in a limiting dilution format in the presence of raltegravir, to avoid new rounds of infection." (PMID 30316868, 2018). "To this end, we performed flow cytometric analysis of lung cells from WT and KO mice following infection with S. aureus and found that NLRP6 KO mice had more IFN-γ-positive NK and CD4+T cells." (PMID 30248149, 2018). "Unfortunately, but not unexpectedly given the size of the Cas9 gene, retroviral transduction of anti-CD3/anti-CD28 stimulated cultured mouse CD4+ T cells resulted in very low (∼5%) transduction rates, as indicated by GFP expression 48 h after infection." (PMID 29436394, 2018). "Then, 24 hours post infection (hpi), the amount of GFP positive cells in various PBMC sub-populations that was defined via staining of the surface markers CD14, CD19, CD3, CD4, CD8 and CD56, followed by flow cytometry analysis." (PMID 29367743, 2018). "Downregulation of CCR7 and CD45RA on a subset of CD4+ and CD8+ T cells was detectable in the blood and spleen of NRG-HIS mice upon YFV-17D infection, indicating that the engrafted HIS responded to the infection." (PMID 30487575, 2018). "Ten days after infection, there was a decrease in the CD4+ and CD8+ T cells population, while the inflammatory cell population remained high (P < 0.001–0.0001) up to 14 to 21 days post-infection." (PMID 30500862, 2018). "In our murine model of memory formation, the expression of KLRG1 was significantly upregulated on CD4 (p = 0.0126) and CD8 (p < 0.0001) T cells in mice that received all three infections compared with mock-infected mice." (PMID 29963060, 2018).
infection (continued). "As the infection persists, the frequencies of HCV-specific CD8 and CD4 T cells detectable in peripheral blood are dramatically reduced." (PMID 30002657, 2018). "In this study, not only CD4 T cells, but also robust cross-reactive antibodies and CD8 T cell immune responses were induced by sequential infection." (PMID 30356772, 2018). "CXCR3 is a chemokine receptor that is highly expressed on effector CD4+ and CD8+ T cells and grants them entry into otherwise restricted sites of Th1-type inflammation and infection." (PMID 29515587, 2018). "Moreover, a much lower number of CD4+ T cells and monocytes were present in the popliteal lymph node (pLN) draining the right footpad, indicating the possible egress of these cells from the pLN into the circulation or infected tissues during enhanced infection." (PMID 29382880, 2018). "On both days 25- and 46-post infection, the frequency of PD1 expressing CD8+ and CD4+Foxp3- T cells were higher in IFNARfl/fl x Foxp3YFP-Cre mice." (PMID 29672594, 2018). "DENV/ZIKV coinfection decreased the ability of CD4+ T cells to produce IFNγ+, TNF+, TNF + IFNγ+, and TNF + IL2+, compared to DENV and ZIKV infections." (PMID 29282904, 2018). "Both Cd2ap−/− and control LCMV-specific CD4 T cells differentiated into Ly6C+ TH1 effector cells or TFH cells as defined by CXCR5 and PD-1 expression on day 8 after infection." (PMID 29734372, 2018). "Cross-reactive spleen CD4+ IFN-γ+ T cell responses against the historical H1N1 strain, A/PR/08, and to the contemporary B strain, B/Bris/60, were still apparent at 42d post-infection." (PMID 29666412, 2018). "This was accompanied by increased numbers of CCR5+CD4+ T cells in the endocervical canal, which suggests that high microbial diversity increases the likelihood that HIV will establish productive infection upon exposure." (PMID 29309550, 2018). "Both memory CD4+ and CD8+ T cells can act against infections with influenza virus, lymphocytic choriomeningitis virus, herpes simplex virus, mycobacterium tuberculosis and parasites." (PMID 29900173, 2018). "Five days post-infection, percentages and numbers of CD39+ CD4+ and CD8+ T cells as well as the mean CD39 expression level on CD4+ and CD8+ T cells were increased." (PMID 29742141, 2018). "It has been reported that skin infection with C. albicans in humans or mice leads to formation of IL-17-producing CD4 TRM cells that reside in papillary dermis and rapidly clear the infection after re-exposure to the pathogen." (PMID 30147701, 2018). "In the RH group, there was an increase in Tim-3 expression on the splenic CD3+CD4+ Th cells (right) accompanied by a reduction of CD3+CD4+ Th cells (right) on day 3–9 post-infection." (PMID 30564216, 2018). "Our group largely studies the epigenetic events in CD4+ and CD8+ T effector cells due to the interaction with Treg cells during FIV infection." (PMID 29710792, 2018). "A phenotype of CTL (CD4+CD8+high) killed infected cells within 3–6 hours after cell infection and another phenotype (CD4+CD8-) killed infected cells at 16–24 hours after infection." (PMID 30188946, 2018). "In the αβ T cell compartment, reductions in IFN-γ- and TNF-α-producing CD4+ and CD8+ T cells were observed after 6 days of P. yoelii 17XNL infection." (PMID 30619302, 2018). "With regard to EV-A71 infection, we reported that the responses of endogenous type I or type II IFNs, CD4 T cells, CD8 T cells, B cells, or antibody in mice provide resistance to infection by reducing tissue viral loads." (PMID 30111869, 2018). "Infection of AG129 mice with PE243 resulted in CD8+ and CD4+ T cell activation, including the activation of TFH, but was unable to significantly increase the number of GC-B cells." (PMID 30087337, 2018). "Immune responses against Lm commence with an early innate phase including macrophages, inflammatory monocytes, NK-cells, DCs, CD4+, CD8+ and γδT cells that together constrain the infection." (PMID 30475900, 2018).